ALB (albumin)
Diseases named in the same sentence as ALB in open-access papers (continued):
Sharing a sentence is not in itself a finding about the gene and the disease.
Sepsis (continued). "Moreover, a high serum-BUN-to-albumin ratio was found to be a good predictor of mortality in patients with sepsis and septic shock." (PMID 36828485, 2023). "In sepsis from AL, a vicious cascade of events ensues where inflammation induces anorexia and reduces the effective use of dietary protein and energy intake, and augments further catabolism of the key somatic protein, albumin." (PMID 37256440, 2023). "Accumulating data indicate a link between albumin functionality and sepsis pathophysiology." (PMID 37628734, 2023). "We performed a univariate logistic regression analysis, and the result showed that age, gender, ethnicity, potassium, calcium, albumin, hemoglobin, ALP, vasopressor, Elixhauser score and respiratory failure were associated with one-year mortality of sepsis patients, which were possible predictors." (PMID 37807068, 2023). "However, research indicates that elevated ferritin levels and decreased albumin levels serve as important markers for mortality and prognosis in sepsis patients." (PMID 37817258, 2023). "In sepsis, the role of albumin is less clear and complex owing to the heterogeneity of sepsis." (PMID 38139434, 2023). "This meta-analysis found, through probability-based ranking, that 4-5% albumin may lead to lower 28-day mortality compared to 20% albumin and crystalloid for patients with severe sepsis." (PMID 37779759, 2023). "Albumin replacement also led to a lower incidence of 90-day mortality in a sub-group of patients with septic shock but provided no added benefits for the 28 and 90-day mortality for patients with severe sepsis." (PMID 37779759, 2023). "With low albumin levels, its effects are limited, so patients become more prone to sepsis." (PMID 37809261, 2023). "In addition, albumin synthesis in the liver is decreased by sepsis-related liver failure and general inflammation, making albumin a negative acute-phase protein." (PMID 37600769, 2023). "The importance of albumin dose, duration, and specific clinical context for its efficacy in the management of decompensated cirrhosis is reiterated, and insights into its potential implications for the management of sepsis are offered." (PMID 38139434, 2023). "Additionally, several studies have demonstrated that albumin is a suitable biomarker for predicting severe sepsis and mortality in patients with ICH." (PMID 37388726, 2023). "Serum albumin levels have been recently found to predict the severity of sepsis." (PMID 38137746, 2023). "Regarding another non‐SARS‐CoV‐2‐targeting blood‐derived product, the Surviving Sepsis Campaign (SSC) suggested the use of albumin combined with large volumes of crystalloids over the use of standalone crystalloids for adult patients with septic shock or sepsis." (PMID 38020714, 2023). "An interesting study is that we developed a prediction model integrating LDH and age, gender, ethnicity, potassium, calcium, albumin, hemoglobin, ALP, vasopressor, Elixhauser score and respiratory failure to predict the risk of one-year mortality for sepsis patients." (PMID 37807068, 2023). "This review explores the role of albumin in sepsis based on its efficacy in cirrhosis." (PMID 38139434, 2023). "The impact of BUN and albumin on the prognosis of patients with sepsis has been demonstrated." (PMID 37340147, 2023). "Identifying the sepsis subgroups that could benefit from albumin is key for effective clinical study design and optimization." (PMID 38139434, 2023). "Serum albumin levels are decreased in most patients with sepsis, although it remains unclear whether this is due to suppressed albumin production or increased albumin clearance." (PMID 37600769, 2023). "The CAR has recently been recognized as more useful than CRP or albumin alone for sepsis." (PMID 37576105, 2023). "We would like to add our considerations on changes in sepsis other than albumin." (PMID 36832250, 2023).
Sepsis (continued). "Regarding laboratory results at admission, increased levels of white blood cell (P < .0001), CRP (P < .0001), PCT (P < .0001) and serum creatinine (P < .0001), while decreased levels of blood platelet (P = .0287) and albumin (P = .0003) were observed in sepsis patients compared to HCs." (PMID 36961174, 2023). "However, albumin levels in acute conditions, including sepsis, decrease in response to various inflammatory effects, such as vascular permeability, dilution, Zn deficiency, and others." (PMID 36832250, 2023). "The use of albumin in sepsis presents contrasting effects and is controversial." (PMID 38139434, 2023). "Serum albumin values have been recently found to correlate with the severity of sepsis." (PMID 38137746, 2023). "Based on this information, we propose that FAR may hold greater significance in the context of sepsis compared to individual measurements of ferritin and albumin." (PMID 37817258, 2023). "Albumin was shown to be a good predictor of short- and long-term outcomes in various settings, such as patients with acute coronary syndrome, acute heart failure, stroke, sepsis, chronic kidney disease, and in older patients." (PMID 37108536, 2023). "Additionally, a similar study demonstrated a trend toward reduced 90-day mortality in patients with severe sepsis given albumin when compared to crystalloid and saline solutions." (PMID 36909040, 2023). "In addition, various studies have indicated that a lower albumin level is related to increased intra-hospital mortality after sepsis, septic shock, ICH and community-acquired bloodstream infections." (PMID 37240644, 2023). "Serum albumin is prematurely lost from the vessels to the interstitium as initial endothelial changes develop due to the cytokine storm in response to infection, resulting in capillary leak syndrome characteristic of the early stages of sepsis." (PMID 38137746, 2023). "In the “Fluid Resuscitation In Sepsis-induced hypotension among patients with Cirrhosis” (FRISC) trial involving cirrhotic patients with sepsis-induced hypotension, 5% human albumin led to better hypotension reversal, improved hemodynamics, and higher short-term survival compared to saline." (PMID 38139434, 2023). "Low albumin levels, a negative acute phasereactant, due to sepsis developing in infective endocarditis patients cause anincrease in ALBI score." (PMID 36459475, 2023). "Serum albumin was significantly decreased in sepsis, which was attenuated by dexamethasone." (PMID 35330172, 2022). "The role of albumin infusion in sepsis patients has been extensively studied in recent years." (PMID 35721190, 2022). "Previous studies have found high high-Sensitive C-Reactive protein/albumin ratio and low AGR could both serve as an independent risk factor of sepsis after PNL and fURS respectively." (PMID 35495750, 2022). "Thus, the effects and safety of albumin infusion in patients with sepsis, especially those with the basic cardiovascular disease, remain controversial." (PMID 36337861, 2022). "Many researchers pay close attention to the relationship between sepsis and ALB." (PMID 36189371, 2022). "Regarding the effect of albumin on the prognosis of patients with sepsis, the Saline versus Albumin Fluid Evaluation (SAFE) study determined that albumin infusion did not damage renal or other organs and may reduce the risk of mortality." (PMID 36337861, 2022). "Fluid resuscitation of albumin is critical in the early stages, especially in patients who require abundant crystalloid resuscitations, but given that patients with early sepsis are always in a state of multiple organ failure, early albumin infusion effects are difficult to detect." (PMID 36337861, 2022). "A recent review highlighted the importance of albumin as a carrier of sphingosine-1-phosphate and its effects on the endothelium, which may benefit the microcirculation of patients with sepsis." (PMID 36555895, 2022).
Sepsis (continued). "After removing patients who had received human serum albumin infusion 3 days before ICU admission, sensitivity analyses showed that there was still a significant association between B/A and poor clinical outcomes in patients with sepsis." (PMID 36577937, 2022). "During the hypermetabolic and hypercatabolic state in sepsis, albumin catabolism was enhanced." (PMID 36053443, 2022). "Increasing evidence suggests that the effect of albumin treatment may be heterogeneous in patients with sepsis, particularly in those with organic heart disease." (PMID 36337861, 2022). "As the bacterial injection progressed to sepsis, lactate, creatinine, and bilirubin increased, while urine output, the ratio of arterial oxygen (PaO2) to fraction of inspired oxygen (FiO2) (P/F) ratio, and albumin decreased." (PMID 35862959, 2022). "Albumin is a fluid often used for resuscitation in patients with sepsis." (PMID 36337861, 2022). "The production and metabolism of serum albumin are severely disrupted in patients with sepsis." (PMID 36337861, 2022). "Additionally, the levels of LDH and albumin were attenuated in the presence of curcumin in the LPS-induced sepsis mouse model." (PMID 34976224, 2022). "Therefore, previous scholars introduced some albumin-based ratios for the diagnosis and prognosis of sepsis." (PMID 36407534, 2022). "In addition to these, the depletion produced by the hypermetabolic state of sepsis patients and the gastrointestinal dysfunction can lower the level of ALB." (PMID 35850582, 2022). "Thus, the effects and safety of albumin infusion in patients with sepsis, especially those with a basic cardiovascular disease, remain controversial." (PMID 36337861, 2022). "In addition, albumin puts an antioxidant influence and it is known that oxidative stress can be a significant characteristic of sepsis pathogenesis." (PMID 36721617, 2022). "So, whether it is necessary to supply albumin to patients during post-operative sepsis is still controversial." (PMID 35495750, 2022). "Additionally, albumin depletion in sepsis correlated with lower plasma free thiol levels, emphasizing the potential importance of albumin as an antioxidant." (PMID 35624664, 2022). "Albumin administration is often used in two conditions in sepsis." (PMID 36337861, 2022). "As a result, decreased ALB concentrations were indicative of sepsis." (PMID 36189371, 2022). "Serum albumin has also been reported to be a biomarker of prognosis in patients with sepsis." (PMID 36211519, 2022). "Additionally, RM administration revealed a significant suppression on plasma contents of ALT, and an increase in the ratio of ALB to GLB compared to the sepsis mice." (PMID 35345558, 2022). "However, there are no available data regarding the clinical value C-reactive protein-to-albumin ratio (CAR) in identifying sepsis in neonates with pneumonia." (PMID 35873709, 2022). "Similarly, higher albumin levels were shown to be a protective factor for sepsis development within 48 h of admission in our study and would need to be adjusted accordingly." (PMID 36464717, 2022). "The fibrinogen to albumin ratio, as an inflammatory serum biomarker, has been identified in several studies as a predictor of poor outcome and adverse events in patients with cardiovascular diseases, cancer, sepsis, and stroke." (PMID 35887976, 2022). "In addition, CAR has recently been considered a more useful indicator of sepsis than CRP or ALB alone in adults." (PMID 35873709, 2022). "It is clear that the impaired serum albumin (SFA)–membrane interaction activity in patients with sepsis was due to albumin-FA binding sites being occupied by pre-bound FA, which were presumably derived from sPLA2-hydrolyzed phospholipids in membranes of massively injured cells in sepsis." (PMID 36232977, 2022).
Sepsis (continued). "Furthermore, a meta-analysis reported a lower mortality rate in patients who suffered from sepsis and received resuscitation with a solution containing albumin than in patients who received other liquid resuscitating regimens." (PMID 35931952, 2022). "The primary purpose of the study was to determine whether ambulation ability with albumin and C-reactive protein are predictive of 28-day mortality of elderly patients with sepsis." (PMID 35962331, 2022). "Although we did not clearly observe a significant decrease (p = 0.061) in these antioxidant parameters during patient follow-up, other studies have reported decreased antioxidants levels accompanied by lower albumin levels after clinical recovery from severe sepsis." (PMID 35448461, 2022). "Unlike albumin and fURS, positive urine culture has been proved to serve as an independent risk factor of sepsis in many previous studies." (PMID 35495750, 2022). "As a result, if sepsis is suspected, Albumin levels should be monitored at the time of entry." (PMID 36189371, 2022). "In the present study, dogs in the septic group had significantly higher bilirubin and lower albumin concentrations compared to the ill and the orthopedic control groups, which is in agreement with other studies in the literature regarding patients with sepsis." (PMID 36423076, 2022). "Everyday weight gain, digestive intolerance (vomiting and/or abdominal distension), sepsis, hospital stay, electrolyte imbalance (derangement of serum sodium, potassium, chloride, and magnesium levels), albumin, and cholesterol/triglyceride levels were assessed." (PMID 35399403, 2022). "Thus, human plasma albumin is an important circulating antioxidant and holds promise for the treatment of sepsis." (PMID 35624664, 2022). "Other emerging sepsis biomarker is the lactate to albumin (L/A) ratio." (PMID 35906231, 2022). "In this study, we sought to evaluate whether albumin combined within a specific time, compared to receiving crystalloids alone, would have a beneficial effect on survival in patients with sepsis." (PMID 33689042, 2021). "Thus, a number of studies have investigated the relationship between the serum CRP/albumin ratio and inflammatory diseases such as sepsis, cancer, acute pancreatitis, ulcerative colitis, hepatitis B, and CAD." (PMID 33453709, 2021). "Low serum albumin levels result in increased mortality in patients with severe sepsis." (PMID 34285680, 2021). "Sepsis acutely decreases the interstitial pressure by several multiples due to protease-mediated cleavage of interstitial matrix elements, which increases capillary filtration and promotes interstitial accumulation of fluid and albumin." (PMID 34448075, 2021). "In our study, survivors recovered normal albumin and protein levels post sepsis." (PMID 34869619, 2021). "We, therefore, hypothesized that combining with albumin within the first 24-h after initiation of crystalloids administration, would increase the survival time in patients with sepsis." (PMID 33689042, 2021). "Folglich untersuchte die randomisierte kontrollierte ALBIOS-Studie (Albumin Italian Outcome Sepsis study) den möglichen Einfluss einer Albumingabe und Aufrechterhaltung des Albumin-Serum-Wertes bei 1810 Patienten mit schwerer Sepsis und septischem Schock auf das Outcome." (PMID 33787990, 2021). "On admission, CRP and CRP/Albumin ratio were higher among patients admitted to ICU with sepsis." (PMID 35199783, 2021). "The indications for albumin use with the largest number of patients over the 6-month study period were sepsis or septic shock (25.3%), hypotension or hypovolemia (19.4%), intra-dialytic hypotension (13.4%), fluid support in surgery (10.8%), and nephrosis or nephropathy (10.8%)." (PMID 34613990, 2021). "Finally, both of these treatments have their counter-indications, for example hemodynamic instability, sepsis and hypersensitivity to albumin for PLEX, and renal failure, hypercoagulable states and hypersensitivity to immunoglobulin for IVIg." (PMID 34599742, 2021).
Sepsis (continued). "Fifteen days after cecal ligation and puncture (CLP), sepsis-surviving BALB/c mice were subjected to a tubulointerstitial injury through intraperitoneal injections of bovine serum albumin (BSA) for 7 days, called the subclinical acute kidney injury (subAKI) animal model." (PMID 34769064, 2021). "Lactate/albumin (L/A) ratio is a biomarker in sepsis that has been shown to outperform lactate." (PMID 34854770, 2021). "However, in the subset of patients with sepsis, there was a trend toward decreased mortality in patients that received albumin compared to 0.9% sodium chloride (30.7 vs. 35.5%, RR 0.87, 95% CI: 0.74–1.02, p = 0.09)." (PMID 33718468, 2021). "In addition, our data indicated that there is a statistical correlation in vitamin E and albumin and HB levels in children with sepsis and septic shock." (PMID 34222298, 2021). "Predictors of complication included preoperative sepsis and lower preoperative albumin." (PMID 34123604, 2021). "Furthermore, several studies have revealed that low serum albumin concentration had the effect on increased mortality in those with pneumonia, sepsis or cancer." (PMID 34943582, 2021). "Then, we verified renal damage in sepsis-surviving mice, being characterized by higher levels of the urinary protein and creatinine (UPCr) ratio, which was aggravated when post-septic mice were challenged with intraperitoneal bovine serum albumin (BSA)." (PMID 34769064, 2021). "This RCT aimed to answer the question of whether in patients with severe sepsis or septic shock, administration of 20% HSA to maintain a serum albumin level ≥3 g/dl (≥30 g/L) reduces all-cause mortality at 28 days compared with no albumin." (PMID 34277747, 2021). "The evidence for albumin benefit in sepsis or septic shock is unclear." (PMID 34613990, 2021). "Most likely, due to its antioxidant properties, albumin restored respiratory dysfunction in sepsis." (PMID 33732938, 2021). "Nevertheless, guidelines from SSC suggest albumin in addition to crystalloids for initial resuscitation and subsequent intravascular volume replacement in patients with sepsis and septic shock when patients require substantial amounts of crystalloids (weak recommendation, low quality of evidence)." (PMID 33689042, 2021). "Albumin has previously been described as an independent factor for mortality in other conditions such as cardiovascular disease, osteoporotic hip fracture, stroke and also sepsis." (PMID 34768653, 2021). "Although these doses are lower than those typically administered in Western countries, the administration of dexmedetomidine at these lower doses successfully decreased CRP and PCT levels and increased albumin levels when administered to patients with sepsis for 14 days." (PMID 32778146, 2020). "In this study, compared to the sepsis group, the KD group showed a significant decrease in albumin." (PMID 32792679, 2020). "This study is aimed at investigating whether albumin-to-fibrinogen ratio (AFR) could independently predict the prognosis in patients with peritonitis-induced sepsis." (PMID 32454793, 2020). "Therefore, based on our findings, NPAR, a new biomarker composed of neutrophil percentage and albumin that closely related to the inflammatory response, can significantly predict the prognosis of sepsis." (PMID 32238212, 2020). "Their AUC for the L/A ratio was 0.69 and was significantly higher than that of lactate (0.62) for predicting 28-day mortality, and these results are comparable with ours and reinforce the finding that the lactate to albumin ratio outperforms lactate alone as a prognostic marker in sepsis." (PMID 33072780, 2020). "We postulate that albumin therapy to replace bound albumin might alleviate some of the symptoms leading to sepsis and that clinical trials to test this postulation should be initiated as a matter of urgency." (PMID 33088822, 2020).